CD14 (CD14 molecule)
Diseases named in the same sentence as CD14 in open-access papers (continued):
Sharing a sentence is not in itself a finding about the gene and the disease.
Sepsis (continued). "Extensive research also demonstrates CD14's pivotal role in initiating and maintaining the pro-inflammatory response during sepsis, which is essential for combating infections and preventing secondary infections in sepsis patients." (PMID 40168842, 2025). "While the K variant exhibited superior efficacy in LPS-induced shock, its disrupted CD14 interactions rendered it ineffective in polymicrobial sepsis." (PMID 40994009, 2025). "In contrast, sHVF18, by engaging both LPS and CD14, effectively reduced inflammation and improved survival in polymicrobial sepsis." (PMID 40994009, 2025). "Only three significant associations were validated in GWAS lookups, with rs2569190 in CD14 remaining significant for 28-day survival in sepsis patients after multiple testing correction." (PMID 40168842, 2025). "Single-cell sequencing analysis suggests that CD16+ and CD14+ monocytes are key immune subgroups in the pathogenesis of sepsis." (PMID 41246299, 2025). "Together, these data demonstrate a significant upregulation of SLC25A33 in LPS/IFN-γ-stimulated macrophages and CD14+ monocytes from human sepsis, suggesting a potential role for SLC25A33 in dysregulated inflammatory responses." (PMID 40384854, 2025). "The authors showed that patients with sepsis-related ARDS had a significantly higher number of CD14+ and CD81+ (CD14+/CD81+) sEVs, resulting from monocytes, than patients with sepsis without ARDS." (PMID 41010852, 2025). "Our study identified CCR2 on CD14 − CD16 + monocytes, as participants in the innate immune response, to be inversely associated with the risk of developing sepsis." (PMID 40797460, 2025). "CD15+CD14+ monocytes, CD45RA−17A+CD4+ T cells, CD45RA−CX3CR1+CTLA4+CD4+ T cells, and Ki67+ B cells were significantly increased in patients with sepsis, with the CD15+CD14+ monocytes having the largest normalised effect size in sepsis." (PMID 40433376, 2025). "We then assessed the expression of individual neutrophil-like and DC-like genes by CD14+ monocytes using bulk RNAseq data from multiple distinct cohorts of patients with sepsis or pneumonia." (PMID 40475424, 2025). "We found that CD14+ monocytes also exhibited the highest module scores in the sepsis group, significantly surpassing those of other cell types." (PMID 39993996, 2025). "For Sepsis, 250 DEGs, including 147 upregulated genes and 103 downregulated genes within CD14+ monocytes, were identified when sepsis patients were compared to healthy controls." (PMID 39993996, 2025). "Recent research has found that CD14+ macrophages and neutrophils are closely associated with the induction and progression of cytokine storms driven by TNF responses in a mouse sepsis model, significantly contributing to lethality." (PMID 40690812, 2025). "The essential role of the evolutionarily conserved N-terminal histidine for CD14 interactions and therapeutic efficacy was demonstrated using LPS-induced shock and polymicrobial sepsis models." (PMID 40994009, 2025). "Our MR analysis revealed that the proportion of CD14+ CD16+ monocytes relative to the total monocyte population played a pivotal role in all three sepsis outcomes, demonstrating a direct correlation with disease severity." (PMID 39076981, 2024). "In our analysis, increased TLR4 expression was noted in sepsis patients, it was supposed that increase in CD14 expression should occur in LPS stimulated macrophages." (PMID 39294473, 2024). "Recent single-cell RNA sequencing investigations identified an immature bone-marrow-derived CD14+ monocyte phenotype with immune suppressive properties termed “monocyte state 1” (MS1) in patients with sepsis." (PMID 38504349, 2024). "A so-called unconventional CD15+ CD11b+ CD14+ CD33+ CD66b+ HLA-DR− subset increased early during sepsis and returned to physiological levels in survivors." (PMID 38391927, 2024).
Sepsis (continued). "LPS is an important medium for sepsis and can activate LPS-binding protein complex of CD14/TLR4 receptor on some types of cells, such as monocytes, and macrophages, thereby inducing the production of inflammatory mediators." (PMID 38297223, 2024). "The same trend was seen in the validation cohort and higher CD206 expression was found on CD14+ monocytes from patients with sepsis and reflects immunological behaviour that will require further research in a larger cohort of patients." (PMID 38588014, 2024). "Upregulated genes, such as FBXO7, appeared to be the promising peripheral biomarkers of SCM, which are differentially expressed across a series of cell subpopulations (B cell, CD14+ monocyte, and plasma cell) in the peripheral blood of patients with sepsis." (PMID 38291374, 2024). "Presepsin is a soluble CD14 subclass which is considered as a marker for patients with sepsis, many studies report its role in detecting sepsis, its severity and outcome." (PMID 39354444, 2024). "FCGR3A+ monocytes, and CD14+ monocytes from the sepsis patients presented the highest PGK1 expression compared to the other patients and other cell types." (PMID 39712033, 2024). "Second, Toll-like receptor-4 (TLR4) and CD14 antagonists are being explored as therapeutic drugs for sepsis." (PMID 39606629, 2024). "Presepsin (PSP), also known as soluble CD14 subtype (sCD14-ST), has emerged as a promising biomarker for early sepsis diagnosis." (PMID 38928726, 2024). "In a neonatal population, sepsis patients exhibited a significant increase in CD14 + + CD16 − monocytes compared with controls, and CD14 + + CD16 − monocytes demonstrated better diagnostic and prognostic abilities in ROC analysis." (PMID 36721090, 2023). "Firstly, we found that CD14+ monocytes from pneumonia-induced sepsis patients had considerably greater levels of the proteins TLR4, NLRP3, ASC1, cleaved caspase-1, IL-1, and GSDMD in contrast to pneumonia patients without sepsis and healthy people." (PMID 36923408, 2023). "Numerous publications, dating back 20 years, support use of either HLA-DR+ CD14+ cells or the actual number of HLA-DR proteins on CD14+ monocytes as clinically useful biomarkers for identifying patients with sepsis." (PMID 36825018, 2023). "Further pathway analysis substantiated that the transcription factors CEBPD and RUNX1, known to be activated temporarily during steady-state and sepsis-induced myelopoiesis, were featured in CD14 Mono_Activated." (PMID 37821442, 2023). "Our study demonstrated that the percentage of MO3 monocytes (CD14 + CD16 + +) was higher in all Chinese Han older adult sepsis patients than in controls." (PMID 36721090, 2023). "CD14+ monocytes are the major subpopulation of monocytes, and several clinical studies have shown that changes in the number and function of circulating CD14+ monocytes in patients with sepsis." (PMID 36923408, 2023). "P2X7R-induced CD14 release in EVs ensures the maintenance of elevated concentrations of circulating CD14 which, by acting as a co-receptor for LPS, is fundamental to controlling infection and increasing survival during sepsis." (PMID 37372953, 2023). "Presepsin, the soluble fraction of cluster of differentiation 14 (CD14), is a sepsis biomarker that is released into circulation when monocytes are activated after binding with lipopolysaccharides (LPS) and LPS-binding proteins." (PMID 37324133, 2023). "Comparison of upregulated genes of mM03 vs. mM06 further substantiated that mM03 and mM06 were corresponded to CD14+HLA-DRhigh and HLA-DRlowS100Ahigh monocytes in human sepsis, respectively." (PMID 37337301, 2023). "Our finding of the increased MO3 (CD14 + CD16 + +)/monocyte percentage in older adult Chinese Han sepsis verified the role of CD14 + CD16 + + monocytes in the occurrence of this disease." (PMID 36721090, 2023).
Sepsis (continued). "It was further uncovered that sepsis patients had an increased number of MDSCs of varying phenotypes (CD14 + HLA-DR- monocytic (M)-MDSC, CD14-CD15+ low-density granulocytes/granulocytic (G)-MDSCs)." (PMID 37185755, 2023). "By exploring the temporal changes in the transcriptome profile from the bacterial induced sepsis and mild COVID patients, we found dramatic differences that predominantly involved CD14+ monocytes following sepsis recognition." (PMID 36979757, 2023). "The CD14+ monocytes of patients with bacterial induced sepsis demonstrated an intense response to stimulation, stress, and inflammatory behaviors." (PMID 36979757, 2023). "During gram negative septicemia, lipopolysaccharide binding protein binds the lipid A moiety of lipopolysaccharide (LPS; endotoxin) and transfers LPS to soluble (plasma) CD14 or membrane-bound CD14 on macrophages." (PMID 36707633, 2023). "Due to the markedly downregulated expression of circ_0075723 in CD14+ monocytes from pneumonia-induced sepsis patients, we next examined the specific role of circ_0075723 in pyroptosis of pneumonia-induced sepsis." (PMID 36923408, 2023). "The effectiveness of the complement inhibition therapies at the C3 level (compstatin) and C5 level (RA101295), along with CD14 inhibition monotherapy were already proven to be beneficial in porcine and baboon sepsis models." (PMID 36059503, 2022). "Recently, WISP1 was shown to promote the inflammatory response via TLR4/CD14 pathways in sepsis-induced lung injury." (PMID 36352407, 2022). "In contrast, neutrophil CD16 and monocytes CD64 and CD14 lost the capacity to predict sepsis in critically ill patients." (PMID 36358327, 2022). "By contrast, another study reported a decreased surface CD14 expression in sepsis/septic shock patients." (PMID 36687421, 2022). "In these studies, the complement or CD14 inhibition attenuated the sepsis-induced inflammation and coagulopathy, displayed protective effects on the endothelium, and was associated with improved organ performance." (PMID 36059503, 2022). "New biomarkers such as presepsin as a soluble CD14 subtype in sepsis patients have been continuously included." (PMID 36969980, 2022). "Using monocytes and dendritic cells, the outcome attained was identification of a sepsis specific CD14+ monocyte state." (PMID 35186993, 2022). "CD14+/CD81+ BAL EV numbers were significantly higher in those patients with sepsis-related ARDS who died during the 30 days following ICU admission." (PMID 35234046, 2022). "To evaluate lncRNA expression in monocytes, we performed RNA sequencing in primary human blood monocytes (CD14+) obtained from patients with sepsis due to community-acquired pneumonia and healthy subjects." (PMID 35903199, 2022). "In this study, we found that LPA3 deficiency promoted the LPS-induced elevation of CD14 expression, caused an up-regulation of TLR4 signaling in monocytes, and aggravated sepsis injury." (PMID 35464399, 2022). "CD14+/CD81+ BAL EV numbers were significantly higher in those patients with sepsis-related ARDS who died during the 30 days following intensive care unit admission (P = 0.027)." (PMID 35234046, 2022). "Previous studies using the combined C5 and CD14 therapy in pigs undergoing sepsis have been based on the “proof of concept” principle where the drug was given before bacteria administration." (PMID 36059503, 2022). "A study of experimental porcine sepsis reported an enhanced efficacy of the combined C5 and CD14 inhibition in limiting the thrombo-inflammation and hemodynamic instability over single monotherapies." (PMID 36059503, 2022). "The relative amounts of circulating CD14-positive monocytes were clearly affected in patients during the transition from non-sepsis to sepsis and subsequently to septic shock independently of diabetes and obesity." (PMID 36687421, 2022). "qRT-PCR and western blotting revealed that CD14 expression was significantly increased in monocytes from Lpar3-/- mice with sepsis." (PMID 35464399, 2022).
Sepsis (continued). "Significant increase in mCD14 MFI values in sepsis patients compared to healthy controls was achieved comparable to CD14%, CD11b%, and CD11b MFI." (PMID 34691286, 2021). "During the progression of the sepsis cascades where the soluble CD14 fragments are cleaved, the soluble CD14 subtype (sCD14-ST) also called as presepsin elevates significantly and is readily measured using a chemiluminescent enzyme immunoassay." (PMID 34150378, 2021). "Presepsin, a subtype of CD14-ST, is secreted from granulocytes by infectious stimuli in an animal sepsis model and can thus be used as a highly specific biomarker for diagnosing bacterial sepsis." (PMID 34193271, 2021). "CD14 (particularly soluble fragments, sCD14) has been mentioned as a possible marker of bacterial infections, including sepsis; however, it probably needs a combination with other markers to provide a reliable diagnosis." (PMID 34054689, 2021). "We observed an overall trend toward decreased HLA-DR expression on CD14+ monocytes meta-clusters in sepsis as compared to HC, which is one of the hallmarks for sepsis." (PMID 33828550, 2021). "To provide more insight into the JAK2-STAT1 pathway relevance in sepsis, we used expression data from CD14+ monocytes isolated from patients with sepsis and healthy age-matched." (PMID 34867954, 2021). "In order to partly address this study limitation, we examined publicly available data on DNA methylation levels in CD14+ monocytes (measured by microarray) from critically ill patients with sepsis due to pneumonia (GSE138074)." (PMID 34399830, 2021). "CD14 was a receptor of LPS and was reported to mediate the occurrence and development of sepsis through the TLR4-NFκB pathway." (PMID 34938184, 2021). "The MS1 and MHC-II gene expression programs were also significantly up-regulated or down-regulated (P < 0.01), respectively, in CD14+ cells derived from HSPCs incubated with sepsis plasma in vitro." (PMID 34103408, 2021). "With regard to CD14 expression, most studies have shown that CD14 expression is upregulated in sepsis." (PMID 34645893, 2021). "Presepsin is a subtype of soluble CD14 (CD14-ST), and is an accurate biomarker for diagnosing sepsis." (PMID 34118899, 2021). "Monitoring of the activation of monocytes and neutrophils was performed by simultaneously analyzing the expression patterns of CD11b, CD88, CD621, and CD14 as well-established markers of the innate immune response after LPS exposure and/or during sepsis." (PMID 33178198, 2020). "The pool of extracellular CD14 in vivo, known as soluble CD14, is detected in different fluids during infection and particularly during sepsis, a life-threating condition resulting from exacerbated inflammation in response to infection." (PMID 33135636, 2020). "In particular, EN-RAGE has been shown to be expressed by CD14+ HLA-DRlo cells, the myeloid-derived suppressor cells, and it is a marker of inflammation in severe sepsis." (PMID 32788292, 2020). "It was proven that antibody-mediated neutralization of systemic CD14 modulates the TLR4 signaling pathway induced by E. coli-derived LPS or virulent E. coli in a pig model of sepsis." (PMID 32842482, 2020). "During sepsis, the elevation of CD14 levels in the serum and peritoneal lavage, also depended on the P2X7 receptor, were important in controlling cytokine secretion, restricting bacterial dissemination and organ damage, increasing overall survival." (PMID 33135636, 2020). "Our data reveal that P2X7 is a key receptor for helping to clear sepsis because it maintains elevated concentrations of circulating CD14 during infection." (PMID 33135636, 2020). "P2rx7-deficient mice present aggravated damage to different organs and premature deaths during sepsis and the administration of recombinant CD14 restores survival in the P2rx7−/−genotype mice." (PMID 33135636, 2020).
Sepsis (continued). "When P2X7 receptor is absent or pharmacologically blocked, the reduced levels of circulating CD14 during sepsis is accompanied by an increase of cytokine release." (PMID 33135636, 2020). "In this study, we comprehensively analyzed the mRNA expression profiles in CD14+ monocytes from critically ill patients and evaluated the usability of regulated monocytic mRNAs as prognostic markers, particularly in sepsis." (PMID 31906585, 2020). "Glucocorticoids have been less well studied in EVD but decrease MHC class II during sepsis and reduce CD14 expression while increasing the abundance of DP monocytes." (PMID 33159858, 2020). "This is similar to the CLP model presented in this study, where while serum IL-6 concentration remains constant between 1 and 2 days of sepsis initiation, CD14 increased." (PMID 33135636, 2020). "Blocking of the cell cycle in CD14+ monocytes is in line with the reduction of classical monocytes in sepsis observed by FACS analysis." (PMID 31906585, 2020). "Phagocytic cells in the blood, such as neutrophils, monocytes, and BDCA1+ CD14− DCs, would serve to defend the bloodstream during early bacteremia to prevent the development of septicemia." (PMID 32698436, 2020). "In order to determine if the P2X7 receptor-dependent release of CD14 during sepsis was impairing LPS-signaling in vivo, we measured cytokines in the serum of P2X7 deficient mice subjected to CLP." (PMID 33135636, 2020). "Many of the cancer patients had levels of CD14+HLA-DRlo/neg monocytes equally high as patients with sepsis." (PMID 31191529, 2019). "While some have reported an increase in intermediate monocytes in sepsis, others demonstrate a reduction of CD14+CD16++ intermediate cells immediately following intravenous infusion of LPS in healthy volunteers." (PMID 31507587, 2019). "In this study, we assess the role of presepsin, which is a CD-14 polypeptide, and procalcitonin which has for some time been the inflammatory marker of choice in sepsis." (PMID 31523578, 2019). "As expected, the population of CD14+CD16++ inflammatory monocytes increased during sepsis, but the surface expression of P2X7 receptors increased in all populations of monocytes." (PMID 31221993, 2019). "Recent research indicates that this CD14+CD16- population of inflammatory monocytes is largely responsible for pathogenic inflammation in arthritis and sepsis, and our data are consistent with these findings." (PMID 31449558, 2019). "CD14+HLA-DRlo/neg monocytes were first characterized in patients with sepsis and were shown to regulate the transition from the inflammatory state to immune suppression, ultimately leading to immune paralysis." (PMID 31191529, 2019). "Presepsin, also known as soluble CD14 subtype, is a protein reported to be increased specifically in the blood of patients with sepsis and is therefore used to predict sepsis in patients in emergency or intensive care units." (PMID 30470216, 2018). "In sepsis, the expression of HLA-DR on circulating CD14 monocytes and the number of HLA-DR molecules (mHLA-DR) on the monocyte surface are decreased and this is interpreted as an index of sepsis-induced immunosuppression." (PMID 29499723, 2018). "Intermediate monocytes (CD14+/CD16+) are elevated in the setting of acute illness such as sepsis in children." (PMID 30390640, 2018). "In two previous studies, one in sepsis and another in acute pancreatitis, the absolute counts of cells highly expressing both CD14 and CD16 were measured; however, the counts of patrolling monocytes were not reported." (PMID 29499723, 2018). "In addition, note that CD14 rs2569190 polymorphism could also influence other sepsis types." (PMID 29426837, 2018). "One hundred ninety-seven of 405 (48.64%) patients with the CD14-159 CC genotype group developed sepsis, as compared to 198 of 383 (51.69%) of those with CD14-159 TT genotype." (PMID 28122493, 2017).